DLL3 (delta like canonical Notch ligand 3)
Diseases named in the same sentence as DLL3 in open-access papers (continued):
Sharing a sentence is not in itself a finding about the gene and the disease.
tumor (continued). "HPN328, a trispecific T-cell activation construct (TriTAC), integrates three functional domains: a DLL3-targeting module for tumor binding, an albumin-binding domain to prolong serum half-life, and a CD3-binding domain for T-cell engagement." (PMID 40496850, 2025). "DLL3 was undetectable in well-differentiated GEP-NETs but expressed in 76.9% of poorly differentiated neoplasms." (PMID 41200177, 2025). "The tarlatamab cases presented were de novo and acquired histologic transformation of SCLC, both with 100% tumor DLL3 expression." (PMID 41256964, 2025). "It consists of two single-chain variable fragments (scFvs)—one that binds DLL3 on tumor cells and another that engages CD3 on T cells—fused to an Fc region that extends serum half-life." (PMID 41415276, 2025). "Rova-T is the first ADC targeting DLL-3, which delivers the cytotoxic payload Tesirine to induce DNA damage and thereby inhibit the proliferation of tumour cells overexpressing this receptor." (PMID 41463450, 2025). "This demonstrates the capacity of DLL3 to function as either an oncogene or tumor suppressor, a role that is dictated by the specific tumor microenvironment and cellular context." (PMID 40066092, 2025). "DLL3 was detected in 81% of NECs, with diffuse expression (≥50% tumor cells) observed in 49% of cases." (PMID 41200177, 2025). "Among six corticotroph tumors that included two densely granulated, three sparsely granulated, and one Crooke cell tumor, two were positive for DLL3 and three for SEZ6." (PMID 40699376, 2025). "DLL3 expression was significantly higher in UCEC tissues compared to adjacent non-tumor tissues, Besides, IHC results also showed higher PCNA and Ki67 expression in patients in the DLL3 high expression group or tumor group." (PMID 40066092, 2025). "Biologically, ASCL1 plays a crucial role in tumor initiation and maintenance by regulating MYCL, SOX2, RET, BCL2, and DLL3, all of which contribute to NE differentiation and tumor survival." (PMID 40333678, 2025). "Subsequent validation in the phase I/II ZENITH trial (NCT04199741) demonstrated [89Zr]Zr-DFO-SC16.56’s ability to discriminate DLL3 expression levels across metastatic sites, with tumor-to-background ratios >5.0 predicting Rova-T response." (PMID 40496850, 2025). "Despite the promising prospects, difficulties remain in the use of DLL3 as a therapeutic target due to tumor heterogeneity, the development of resistance, potential adverse effects, and barriers to patient stratification." (PMID 40284515, 2025). "Although the molecular landscape of SCLC LN metastases largely resembles that of the tumor of origin, key differences exist in terms of DLL3 and NEUROD1 expression, and in subtype distribution." (PMID 40107154, 2025). "Subsequent examination of the excised tumors confirmed a significant reduction in both tumor weight and volume in the DLL3 knockdown group." (PMID 40066092, 2025). "While knocking down DLL3 in HEC-1-A reduced tumor burden, the results remain constrained by these limitations." (PMID 40066092, 2025). "Additionally, upregulation of Delta‐like ligand 3 (DLL3) mRNA in Exo and its membrane protein (mProtein) in extracellular vesicles associated with tumor (tEV) may distinguish both limited‐ and extensive‐stage SCLC patients from high‐risk smokers, with AUC/ROC values of 0.836 and 0.839, respectively." (PMID 40285610, 2025). "The failure of SC-002 further emphasised the class-specific challenges of DLL3-targeting ADCs, notably on-target, off-tumour toxicities, and required innovative engineering to widen the therapeutic window." (PMID 41463450, 2025). "At the same time, tarlatamab binds to DLL3 on the surface of tumor cells, directing the immune response specifically to cancer cells that express this protein." (PMID 40422520, 2025).
tumor (continued). "DLL3’s tumor-specific expression in SCLC offers a viable target, while engineering strategies such as cytokine-secreting “armored” CARs (e.g., IL-12 or IL-18 producers) show promise in overcoming TME resistance." (PMID 40496850, 2025). "DLL3 overexpression confers significant survival advantages to tumor cells since it facilitates cell proliferation and metastasis." (PMID 40284515, 2025). "In two of three patients (patients 5 and 6), DLL3 immunoPET-CT imaging revealed that all individual DLL3 PET-positive tumor lesions also demonstrated SSTR avidity on corresponding 68Ga-DOTATATE PET-CT imaging." (PMID 41264896, 2025). "This Notch-suppressive activity drives the maintenance of neuroendocrine differentiation and stem-like properties in SCLC, as evidenced by ASCL1-dependent transcriptional upregulation of DLL3 in tumor-initiating cells." (PMID 40496850, 2025). "Tarlatamab (AMG 757) is a half-life extended (HLE) BiTE® that targets DLL3 in tumor cells and CD3 in T-cells." (PMID 40507301, 2025). "Tarlatamab (AMG757) is a first-in-class anti-DLL3 x CD3 bispecific T cell engager (BiTE) that binds to DLL3 on the surface of tumor cells and CD3 on cytotoxic T cells, leading to T cell activation and cytotoxic T cell-mediated cell death." (PMID 40565299, 2025). "DLL3 expression has been investigated across diverse neoplasms, revealing distinct biological and clinical patterns." (PMID 41200177, 2025). "Regarding tumour localisation, pulmonary AC (19/39, 48.7%) and TC (37/96, 38.5%) showed a much higher rate of DLL3 positivity compared to GEP-NET (43/845, 5.1%; p < 0.001)." (PMID 40153138, 2025). "Using qRT-PCR, Western blotting, and IHC, we observed a notable increase in DLL3 expression in UCEC tissues compared to adjacent non-tumor tissues." (PMID 40066092, 2025). "Delta-like ligand 3 (DLL3) functions as an inhibitory ligand of the Notch pathway by interacting with Notch receptors (Notch1-4), promoting malignant tumor transformation." (PMID 41375037, 2025). "DLL3 expression has also been found in gastrointestinal mixed adenoneuroendocrine carcinomas, particularly in tumor cells with positive immunoreactivity to chromogranin A." (PMID 41200177, 2025). "In summary, we describe frequent DLL3 IHC expression in high-grade PanNETs and poorly differentiated GEP NECs, nominating these tumor types as key populations for the development of DLL3-targeted therapies." (PMID 41264896, 2025). "Further experimental validation demonstrated that reducing DLL3 expression in tumor cells significantly inhibited their proliferation, migration, and invasion capabilities." (PMID 40066092, 2025). "Delta-like ligand 3 (DLL3), an atypical Notch ligand and novel biomarker of tumor-initiating cells has been identified as a potential target in SCLC." (PMID 40160238, 2025). "Given its frequent overexpression across the wide spectrum of neoplasms, DLL3 represents a compelling therapeutic target for CAR-T therapy in refractory tumors, including lung NENs." (PMID 41200177, 2025). "Due to the relation between DLL3 and ASCL1, and since it is frequently upregulated in neuroendocrine subtypes in SCLC, DLL3 has emerged as a promising therapeutic target in this tumor subtype." (PMID 40075573, 2025). "Key factors include Target Heterogeneity: Only 68% patients had high DLL3 expression (defined as ≥75% of tumor cells), but the phase III TAHOE trial enrolled patients regardless of DLL3 levels, diluting efficacy." (PMID 40496850, 2025). "Preclinical studies demonstrate widespread expression of DLL-3 in tumour neuroendocrine cells, with approximately 80% of SCLC patients harbouring this receptor." (PMID 41463450, 2025). "DLL3 is a common target of bsAbs due to its expression on the surface of over 80% of SCLC tumor cells." (PMID 40507328, 2025).
tumor (continued). "Rova-T demonstrated encouraging antitumor activity as a single agent with confirmed objective response (OR) in 18% of patients and 38% of those with high DLL3 expression (expression in at least 50% of tumor cells)." (PMID 40160238, 2025). "After binding to different Notch receptors (Notch1-4), DLL3 promotes malignant tumor transformation." (PMID 41375037, 2025). "Although the molecular profile of the LN metastases resembles that of the tumor of origin, key differences exist in terms of DLL3 and NEUROD1 expression." (PMID 40107154, 2025). "BiTEs are composed of two single-chain fragment variables (scFvs)—one targeting tumor antigens (e.g., DLL3) and another engaging T-cell CD3—along with an Fc region to prolong serum half-life." (PMID 40496850, 2025). "IHC analysis further underscored this finding, showing reduced proliferation markers Ki67 in the DLL3-suppressed tumors, collectively indicating that DLL3 downregulation curtails tumor proliferation in vivo." (PMID 40066092, 2025). "These therapeutic agents are designed to physically bridge a patient's T cells to the DLL3 protein on tumor cells, thereby inducing targeted cell killing." (PMID 41415713, 2025). "Therapeutically, DLL3’s tumor-specific membrane localization and minimal normal tissue expression render it an ideal target for precision therapies." (PMID 40496850, 2025). "DLL3, a ligand in the NOTCH signaling pathway, is implicated in tumor progression and is expressed in various tumor types, including GBM." (PMID 40565099, 2025). "Nonetheless, certain tumor-associated antigens, including programmed death-ligand 1 (PDL1) and Delta-Like Ligand 3 (DLL3), show promise for targeted antibody-based immunotherapy." (PMID 38468968, 2024). "By harnessing the tumor-specific expression of DLL3 and the therapeutic potential of beta-emitting radioisotopes, this approach offers a novel strategy for precision medicine in SCLC." (PMID 39703856, 2024). "Because we had survival data from our patients, we calculated DFS and OS by taking the cutoff of ≥ 50% positive tumor cells as high expression of DLL3, as previously considered in MTC)." (PMID 38958823, 2024). "By leveraging the tumor-specific expression of DLL3 and the unique properties of photoactivated cytotoxicity, DLL3-targeted NIR-PIT offers the potential for precise and minimally invasive intervention in SCLC." (PMID 39703856, 2024). "Her tumor was found to strongly express DLL3 and had an impressive clinical response to tarlatamab therapy." (PMID 39619276, 2024). "Nineteen cases (30%) expressed DLL3 in less than 50% of tumor cells, while 27 (42%) expressed it in more than 50% of cells." (PMID 39392394, 2024). "The initial human study (FIH) of Rova-T demonstrated an ORR of 18%, which notably increased to 38% among patients with high DLL3 expression in SCLC (defined as DLL3 expression in ≥ 50% of tumor cells as determined by IHC)." (PMID 39152301, 2024). "Liquid biopsies, imaging techniques, and quantitative immunohistochemistry are enabling non-invasive, real-time assessment of DLL3 expression levels, offering a dynamic view of tumor biology during treatment." (PMID 39703856, 2024). "As it happens in our cohort, in both series published, around half of the tumors had high expression of DLL3 (defined as ≥ 50% of positive tumor cells)." (PMID 38958823, 2024). "DLL3 has emerged as a promising target for SCLC due to its high expression in tumor tissues and limited presence in normal tissues." (PMID 39703856, 2024). "DLL3 was detected in 84.5% (82/97) of all patients' tumor samples by IHC, mainly located on the surface of SCLC cells." (PMID 38847733, 2024).
tumor (continued). "Among patients who were DLL3-positive (≥25% of tumor cells positive for DLL3) (287 patients) and patients with high DLL3 positivity (≥75% of tumor cells positive for DLL3) (238 patients), the best ORR was 20.6% and 21.8%, respectively." (PMID 38927637, 2024). "The persistent expression of DLL3 in residual tumor cells post-treatment suggests the potential for fractionated or repeated administrations of [177Lu]Lu-DTPA-CHX-A”-SC16 to enhance therapeutic efficacy." (PMID 39703856, 2024). "DLL3-targeted BiTEs, such as tarlatamab, engage DLL3-positive tumor cells and simultaneously attract T cells to these sites, promoting tumor infiltration." (PMID 39703856, 2024). "DLL3 is considered to inhibit T cell trafficking and infiltration, thereby resulting in the so-called cold tumor microenvironment." (PMID 38483588, 2024). "DLL3 is highly expressed in 72% of primary SCLC tumor tissues and 85% of recurrent SCLC tumor tissues, whereas it is rarely expressed in normal tissues, making it a promising target." (PMID 38429828, 2024). "Rovalpituzumab tesirine (Rova‐T, S16LD6.5) is a novel ADC that targets DLL3, a protein found in certain tumor cells." (PMID 39070179, 2024). "In contrast, DLL3 protein expression in stroma was moderately correlated with tumor size (ρ = 0.276; p = 0.005)." (PMID 37893184, 2023). "Since most of the signaling pathways enriched by KEGG in this study were tumor- and immune-related, we conclude that DLL3 is involved in the development and progression of COAD." (PMID 37274780, 2023). "Overall, this study aimed to evaluate the biological and immunological importance of DLL3 expression in different types of tumor tissues, and provides insight into the role of DLL3 in tumor immunotherapy." (PMID 37179118, 2023). "In contrast, a much smaller study that examined DLL3 expression in 30 paired chemotherapy-naïve and chemotherapy-relapsed SCLC tumor samples found that DLL3 expression increased or decreased following chemotherapy in more than 40% of samples." (PMID 37355629, 2023). "Kolmogorov–Smirnov test supported a normal distribution of DLL3 expression in the tumor samples (p-value = 0.113)." (PMID 37893184, 2023). "As the DLL3 interaction occurs between cells, stroma and tumor cells should be studied together to elucidate all of the interactions between the tumor microenvironment and the tumor cells." (PMID 37893184, 2023). "The key finding of the study indicated that 38% of the patients demonstrated a positive response to treatment with rovalpituzumab tesirine in patients with high DLL3 expression, defined as having ≥50% expression on tumor cells." (PMID 37509621, 2023). "Almost all immune-related genes presented the co-expressed pattern with DLL3 expression, and the most of them were positively correlated with DLL3 in all kinds of tumor except for several types of tumors (SARC, SKCM, TGCT, UVM, and THCA)." (PMID 37179118, 2023). "The relationship between DLL3 expression levels and the tumor infiltrating immune cells were then examined." (PMID 37179118, 2023). "The differences in the expression patterns and subcellular distributions of DLL3 between normal and malignant cells underscore its considerable appeal as a therapeutic target characterized by an intrinsic propensity for tumor selectivity." (PMID 38001628, 2023). "Delta-like ligand 3 (DLL3) has emerged as an attractive tumor-specific target uniquely overexpressed on the cell surface of SCLC and other high-grade NECs." (PMID 37355629, 2023). "Here, the percentage of DLL3 expression in tumor cells ranged from 10 to 100%, with a mean and median value of 64,6% and 70%, respectively." (PMID 37893184, 2023). "In this study, we discussed the biological and immunological significance of DLL3 expression in different tumor tissues." (PMID 37179118, 2023).
tumor (continued). "We utilized the ESTIMATE algorithm to dissect the non-tumor components, stromal and immune parts, so as to delineate the function of DLL3 in tumor microenvironments and the biological tole in cancer immune therapies." (PMID 37179118, 2023). "DLL3, which shows surface expression specific to tumor cells, is thus an attractive therapeutic target, and DLL3-targeted therapies are currently under clinical investigation, with promising antitumor activity demonstrated to date." (PMID 38126617, 2023). "Gene functional enrichment analysis revealed that DLL3-related DEGs were mainly enriched in tumor- and immunity-related signaling pathways, containing AMPK pathway and mitophagy-animal." (PMID 37274780, 2023). "Depending on the cellular context, the single transmembrane protein known as Delta-Like Ligand 3 (DLL3) mediates cell fate decisions and is either tumor-suppressive or carcinogenic." (PMID 37179118, 2023). "In patients with high DLL3 expression (DLL3 expressed by > 75% of tumor cells by IHC), the ORR was slightly higher at 14.3%, with a median progression-free survival (PFS) of 3.8 months and a median OS of 5.7 months." (PMID 37355629, 2023). "The differential expression and localization profiles of DLL3 in normal and tumor cells render DLL3 an attractive, tumor-selective therapeutic target." (PMID 37355629, 2023). "As expected, DLL3 tumor expression was moderately significantly correlated with DLL3 expression in stroma (ρ = 0.4; p = 0.0001)." (PMID 37893184, 2023). "Here, a low positive correlation was found between DLL3 tumor expression and PD-L1 CPS (%) (ρ = 0.188; p = 0.04) as well as a low negative correlation with POLE nuclear expression (%) (ρ = −0.233; p = 0.016)." (PMID 37893184, 2023). "Depending on the tumor type and cell growth environment, activation of DLL3 can play a pro- or anti-cancer role." (PMID 37274780, 2023). "Significant changes in DLL3 expression between tumor and normal tissue were found in 18 different forms of cancer, with the exception of those where there are fewer than five available normal tissues." (PMID 37179118, 2023). "Low DLL3 tumor expression showed a shorter median PFS of 8 months (95%CI: 4.1–11.8 months) compared with the median PFS of the high DLL3 expression arm, which was 17 months (95%CI: 9.6–24.3 months) (p-value = 0.009)." (PMID 37893184, 2023). "Our findings demonstrated that the DLL3 is substantially expressed in 34 different cancer types and has a significant role in tumor immunity by influencing immune cells that infiltrate tumors." (PMID 37179118, 2023). "The identification of DLL3 as a tractable tumor-specific target has led to the design and testing of DLL3-targeting CAR therapies in SCLC." (PMID 37355629, 2023). "In SCLC, there are common inactivating mutations in the primary Notch family members and overexpression of a key negative regulator of Notch signalling known as delta-like protein 3 (DLL3) was found in the majority of SCLC tumours." (PMID 37240229, 2023). "Upregulated DLL3 expression was verified to promote tumor growth in a mouse xenograft model that was implanted with DLL3-overexpressing SBC-5 human SCLC cells." (PMID 35628495, 2022). "In the PDX array, all four of these models had robust DLL3 expression in the majority of tumor cells including some degree of clearly membranous staining." (PMID 36381237, 2022). "There was no significant differential expression of DLL3 and JAG2 between different tumor stages; however, tumors with higher grades showed significantly higher expression of DLL3 (grade III vs. grades I, II; P value < 0.0001)." (PMID 36476410, 2022). "DLL3 localised to the plasma membrane of tumour cells and acted as a reliable biomarker to predict cancer progression and a poor clinical outcome." (PMID 35057823, 2022). "Pre- and clinical trial results indicated that membrane DLL3, a potential target for preventing tumour growth." (PMID 35057823, 2022).